PTGDR2 (prostaglandin D2 receptor 2)
Description:
Receptor for prostaglandin D2 (PGD2). Coupled to the G(i)- protein. Receptor activation may result in pertussis toxin-sensitive decreases in cAMP levels and Ca(2+) mobilization. PI3K signaling is also implicated in mediating PTGDR2 effects. PGD2 induced receptor internalization. CRTH2 internalization can be regulated by diverse kinases such as, PKC, PKA, GRK2, GPRK5/GRK5 and GRK6. Receptor activation is responsible, at least in part, in immune regulation and allergic/inflammation responses.
Synonyms: CD294; CRTH2; DL1R; GPR44; DP2
Tractability: Small molecule: an approved drug acts on it; a structure with a bound ligand is known; a high-quality ligand is known; it belongs to a druggable protein family. Antibody: UniProt places it where antibodies can reach, with high confidence; its Gene Ontology location is reachable by antibodies, with high confidence; UniProt predicts a signal peptide or a membrane-spanning region. PROTAC: a small molecule that binds it is known.
Target class: Lipid-like ligand receptor (family A GPCR); Membrane receptor; Prostanoid receptor; Small molecule receptor (family A GPCR); Family A G protein-coupled receptor
Chemical probes: CHEMBL217053, CRTH2 antagonist (high quality)
Gene: Protein-coding gene on chromosome 11 (60,850,933 to 60,855,950, reverse strand). Ensembl gene ENSG00000183134.
Subcellular location: Cell membrane
Pathways (Reactome):
Signal Transduction: G alpha (i) signalling events; Prostanoid ligand receptors
Gene Ontology:
Molecular function: G protein-coupled receptor activity; prostaglandin D receptor activity; protein binding; neuropeptide binding; prostaglandin F receptor activity; prostaglandin J receptor activity
Biological process: calcium-mediated signaling; chemotaxis; G protein-coupled receptor signaling pathway; cellular response to prostaglandin D stimulus; immune response; neuropeptide signaling pathway; signal transduction
Cellular component: neuron projection; plasma membrane; membrane
Genetic constraint (gnomAD): Missense variants: 264 observed, 247.5 expected, observed/expected ratio (o/e) 1.07, 90% interval 0.96 to 1.18. Synonymous variants: 124 observed, 110.1 expected, observed/expected ratio (o/e) 1.13, 90% interval 0.97 to 1.31.
Homologues: Orthologues: chimpanzee PTGDR2 (99% identical), macaque PTGDR2 (97% identical), pig PTGDR2 (86% identical), dog PTGDR2 (84% identical), rabbit PTGDR2 (82% identical), rat Ptgdr2 (77% identical), mouse Ptgdr2 (77% identical), guinea pig PTGDR2 (72% identical), Caenorhabditis elegans trhr-1 (16% identical), Drosophila melanogaster Rh7 (16% identical). Paralogues in human: LTB4R2 (26% identical), CMKLR2 (25% identical), OPRD1 (25% identical), SSTR4 (24% identical), LTB4R (23% identical), OPRK1 (23% identical), OPRM1 (22% identical), OPRL1 (22% identical), NPBWR1 (22% identical), SSTR5 (21% identical), SSTR1 (21% identical), SSTR2 (21% identical), and 5 more.
Diseases named in the same sentence as PTGDR2 in open-access papers:
PTGDR2 is named in the same sentence as 112 diseases in open-access papers, as found by Europe PMC text mining. Sharing a sentence is not in itself a finding about the gene and the disease. The quoted sentences say what the papers report.
asthma (58 papers, 2006 to 2025). "Although it is highly speculative, maybe the high levels of PTGDR2 expression could suggest a predisposition for evolution to more severe forms of asthma." (PMID 34575604, 2021). "Increased PTGDR2 mRNA levels have also been described in the bronchoalveolar lavage of severe asthma patients." (PMID 34575604, 2021). "PTGDR2 was also found differentially expressed in a sputum cell transcriptomic expression study of 84 subjects with asthma compared to 27 healthy controls." (PMID 34575604, 2021). "There was a moderate positive correlation between PTGDR2 expression and peripheral blood eosinophils count in most asthma groups." (PMID 34575604, 2021). "In the present work, we explored PTGDR2 levels in peripheral blood as a possible biomarker demonstrating differential expression levels between asthmatic and controls and progressively increasing PTGDR2 levels as the severity of asthma raised." (PMID 34575604, 2021). "Fevipiprant, which targets PTGDR2, has been evaluated in clinical trials for asthma and atopic dermatitis; Zileuton, a 5-lipoxygenase inhibitor that reduces leukotriene synthesis, targets ALOX5; and captopril, an angiotensin-converting enzyme inhibitor, targets ACE." (PMID 41395465, 2025). "If this were to occur, the use of PTGDR2 as a biomarker of asthma severity could identify patients long before they have severe asthma episodes." (PMID 34575604, 2021). "Interestingly, the highest PTGDR2 levels (54.1-fold change) corresponded to a young male patient with intermittent asthma and CRSwNP who had asthma exacerbations only when aspirin was taken, without symptoms or needed medication out of these episodes." (PMID 34575604, 2021). "PTGDR2, one of the most differentially expressed genes, was chosen as a candidate because different antagonists against PTGDR2 were being developed as a therapy for T2 asthma." (PMID 34575604, 2021). "Thus, patients with asthma and CRSwNP presented high values of PTGDR2, which were further increased in patients who also presented intolerance to NSAIDs (AERD)." (PMID 34575604, 2021). "A similar result was observed in patients with CRSwNP, in which PTGDR2 expression levels were only increased in patients with concomitant asthma, suggesting that they could also help differentiate CRSwNP patients with and without asthma." (PMID 34575604, 2021). "As PTGDR2 mRNA expression could be a possible biomarker for asthma, a comparison with peripheral blood eosinophil count using an ROC curve analysis was performed." (PMID 34575604, 2021). "Furthermore, patients with mild persistent asthma had the lowest expression levels of PTGDR2 (7.3 ± 5.0), while patients with severe asthma showed the highest levels (12.1 ± 11.2)." (PMID 34575604, 2021). "A combination of PTGDR2 mRNA and blood eosinophils count could provide an optimal predictive value for asthma, CRSwNP, and AERD." (PMID 34575604, 2021). "Similarly, PTGDR2, which we found to be upregulated in male lungs compared to females, is believed to be essential for the pro-inflammatory cytokines induction as well as asthma pathogenesis." (PMID 34604307, 2021). "Concerning these findings, we propose that peripheral blood mRNA levels of different genes (such PTGDR2) should be explored as new minimally invasive biomarkers that might assist in the molecular phenotyping of asthma and selecting patients for treatment with specific antagonists." (PMID 34575604, 2021). "In addition, higher PTGDR2 expression levels were observed as the severity of asthma increased." (PMID 34575604, 2021). "We also found that PTGDR2 was not differently expressed in patients with allergic rhinitis without concomitant asthma, indicating that the levels of PTGDR2 in peripheral blood might help differentiate allergic patients with and without asthma." (PMID 34575604, 2021).
asthma (continued). "Targeting both PTGDR-1 and PTGDR-2 seems a valuable therapeutic approach to prevent flares in patients with SLE and in other diseases involving basophil, PGD2, and CXCL12 such as allergic diseases, chronic urticaria, asthma, inflammatory bowel diseases, and other chronic inflammatory disorders." (PMID 29463843, 2018). "Exploring the CRSwNP patients with or without asthma, we also found a higher (not significant p > 0.05) AUG for PTGDR2 [0.672 (0.566–0.778)] than for eosinophils [0.597 (0.486–0.707)]." (PMID 34575604, 2021). "Finally, in the case of asthma with CRSwNP, with or without NSAID intolerance respiratory, a higher (not significant p > 0.05) AUC was also found for PTGDR2 than for eosinophils." (PMID 34575604, 2021).
allergic disease (25 papers, 2007 to 2025). An immune response that occurs following re-exposure to an innocuous antigen, and that requires the presence of existing antibodies against that antigen. "The role of PTGDR2 and CCL17 (TARC) in the pathogenesis of allergic disease is well‐recognized." (PMID 34637606, 2022). "However, new PTGDR-2 and dual PTGDR antagonists may achieve their clinical development in a near future and obtain approval in allergic disease treatment." (PMID 29463843, 2018).
gastric cancer (13 papers, 2014 to 2024). A primary or metastatic malignant neoplasm involving the stomach. "Overexpression of Yes-associated protein 1 (YAP) suppresses L-Pgds and Ptgdr2 gene expression in gastric cancer cells." (PMID 34744762, 2021). "In addition, the microarray data analysis of 875 gastric cancer patients indicated that upregulation of PTGDR2 expression was significantly associated with a better prognosis." (PMID 38704736, 2024). "Moreover, the down-regulated expression of PGD2 and PTGDR2 has been closely associated with poor prognosis and high mortality in gastric cancer patients." (PMID 38704736, 2024). "PGD2/PTGDR2 signaling was found to inhibit tumorigenesis, tumor growth, and metastasis in gastric cancer." (PMID 36793597, 2023). "Overexpression of L-Pgds and Ptgdr2 genes decreases proliferation and self-renewal of gastric cancer cells by YAP." (PMID 34744762, 2021). "Previous studies show that PTGDR2 inhibits tumor growth and tumorigenesis in gastric cancer and restricts angiogenesis in colon cancer." (PMID 33552958, 2020). "Zhang found that PTGDR2 was abnormally expressed in gastric cancer, which was related to the poor prognosis of patients." (PMID 33029266, 2020). "Altogether, it is tentatively suggested that the PGD2/PTGDR2 signaling pathway may influence gastric cancer development by regulating the ubiquitination of ATG4B." (PMID 39777337, 2024). "Prostaglandin D2 (PGD2) synthase (PTGDS) and its receptor PTGDR2 are negatively correlated with stem genes (Sall4 and Lgr5) in gastric cancer, which restricts tumor self-renewal, growth, and metastasis by relying on the PTGDR2 pathway to inhibit STAT3 phosphorylation and nuclear expression." (PMID 33312950, 2020). "Further study showed that the expression of PTGDR2 reversed these effects, indicating a novel function of PGD2/PTGDR2 signaling on CSC regulation and tumorigenesis in gastric cancer." (PMID 31781593, 2019). "Furthermore, the negative correlation of PTGDR2 with mRNA expression of OCT4, NANOG, LGR5, and SALL4 in cancerous tissues also demonstrated the relevance of these in vitro results to gastric cancer." (PMID 38704736, 2024).
allergic rhinitis (7 papers, 2007 to 2024). Inflammation of the nasal mucous membranes caused by an IgE-mediated response to external allergens. "The highest PTGDR2 expression in Q2 corresponded with a polysensitized allergic rhinitis patient (43.2-fold), and two asthmatic patients with CRSwNP and sensitivity to NSAIDs (AERD) (36.7- and 19.7-fold, respectively)." (PMID 34575604, 2021). "A group of 52 patients who only had allergic rhinitis (AR) was included to analyze the relationship of atopy with the expression of PTGDR2." (PMID 34575604, 2021).
nasal polyps (7 papers, 2015 to 2024). "In another preliminary study, a group from the UK specifically investigated the expression of PGD2 and its receptor PTGDR2 in several samples from nasal polyps and inferior turbinates." (PMID 39595211, 2024). "Moreover, Ptgdr2 transcripts have been found in BMMCs, and CRTH2 immunopositive human mast cells were found in nasal mucosa and nasal polyps, although the expression seemed to be intracellular." (PMID 31191511, 2019).
eosinophilia (5 papers, 2007 to 2022). "In contrast, mice lacking Ptgdr2 have an enhanced BAL eosinophilia in OVA-induced allergic airway inflammation." (PMID 31191511, 2019).
acute myeloid leukemia (4 papers, 2022 to 2025). Acute myeloid leukemia (AML) is a group of neoplasms arising from precursor cells committed to the myeloid cell-line differentiation. "The literature suggested that in addition to solid tumors, PTGDR2 (referred to as GPR44 in that article) activation in acute myeloid leukemia (AML) induces apoptosis of leukemic cells in a mouse model of human leukemia, a human AML cell line, and patient samples." (PMID 38704736, 2024).
colitis (3 papers, 2017 to 2019). Inflammation of the colon. "PTGDR2 also played a proinflammatory role in the TNBS-induced colitis model." (PMID 31781593, 2019).
lung carcinoma (3 papers, 2023 to 2024). "Another microarray data analysis of 504 lung cancer patients indicated that downregulated PGD2 and PTGDR2 expression was associated with a poorer prognosis and lower survival rate." (PMID 38704736, 2024). "In normal or low serum cultured A549 lung cancer cells, PGD2 induced PTGDR2 expression and also regulated EMT by mediating TGF-β1 expression, which in turn affected cell proliferation, migration, and invasion." (PMID 38704736, 2024).
lupus (3 papers, 2018 to 2023). "Overall, we established a proof of concept that AMG853, a clinically relevant bispecific PTGDR-1 and PTGDR-2 antagonist, can control lupus-like inflammation in a manner similar to the combination of PTGDR-1- and PTGDR-2-specific antagonists." (PMID 35444641, 2022). "Here, we aimed at establishing a proof of concept that a clinically relevant bispecific antagonist of PTGDR-1 and PTGDR-2 could be efficient to treat murine lupus-like nephritis." (PMID 35444641, 2022). "Thus, bispecific PTGDR-1 and PTGDR-2 antagonists, such as AMG853, are a promising class of drugs for the treatment or prevention of organ damage in systemic lupus erythematosus." (PMID 35444641, 2022).
Sepsis (3 papers, 2016 to 2022). Sepsis is defined as life-threatening organ dysfunction caused by a dysregulated host response to infection. "CCR3, PTGDR2 (alias CRTH2), and FCER1A are associated with allergic processes and have been described in sepsis and bacterial meningitis." (PMID 30463588, 2018). "The PTGDR2, a chemoattractant receptor molecule (CRTH2), and CCR3, are reported to be expressed on Th2 cells and eosinophils, and their co-expression was linked to Th2 response in sepsis inflammatory response." (PMID 36005179, 2022).
ulcerative colitis (3 papers, 2017 to 2021). An inflammatory bowel disease involving the mucosal surface of the large intestine and rectum. "The high expression level of PTGDR2 was predominantly observed in the mild inflammation in ulcerative colitis patients." (PMID 31781593, 2019).
Crohn disease (2 papers, 2019 to 2021). A gastrointestinal disorder characterized by chronic inflammation involving all layers of the intestinal wall, noncaseating granulomas affecting the intestinal wall and regional lymph nodes, and transmural fibrosis. "Antagonism of PTGDR2 had been shown to promote antiallergic and anti-inflammatory effects in Crohn's disease." (PMID 31781593, 2019).
leukemia (2 papers, 2024 to 2025). A malignant (clonal) hematologic disorder, involving hematopoietic stem cells and characterized by the presence of primitive or atypical myeloid or lymphoid cells in the bone marrow and the blood. "Furthermore, PTGDR2 knockdown causes splenomegaly and the appearance of more and larger leukemia cells in mice." (PMID 38704736, 2024). "Moreover, PTGDR2 has demonstrated special therapeutic effects in leukemia diseases, where it promoted apoptosis and reduced the disease severity by modulating relevant signals." (PMID 38704736, 2024). "In some chronic myeloid leukemia (CML) and AML, especially with high PTGDR2 expression in FAB subtypes M2, M3, and M6, patients showed better survival, suggesting that high PTGDR2 expression might be a target for leukemia therapy." (PMID 38704736, 2024).
Oropharyngeal Cancer (2 papers, 2020 to 2024). Carcinoma, predominantly squamous cell, arising from the epithelial cells of the oropharynx. "Additionally, it has been observed that the downregulated expression of PTGDR2, PTGDR1, and PTGIR genes was associated with a poorer prognosis in oropharyngeal cancer patients, and all three can be used to screen HPV-ctDNA-negative HPV oropharyngeal cancer patients." (PMID 38704736, 2024).
androgenetic alopecia (1 paper, 2018). "Prostaglandin D2 (PGD2) and prostaglandin D2 receptor 2 (DP2) is known to be an important factor in androgenetic alopecia (AGA)." (PMID 29439547, 2018).
Brain atrophy (1 paper, 2020). Partial or complete wasting (loss) of brain tissue that was once present. "In addition, Kiely found that PTGDR2 was abnormally expressed in the microglia of degenerative brain atrophy and may be involved in the inflammatory changes of degenerative brain atrophy." (PMID 33029266, 2020).
breast carcinoma (1 paper, 2024). "Subsequent microarray data analysis of 1089 breast cancer patients revealed that reduced PGD2 and PTGDR2 expression was linked with a worse prognosis and shorter OS." (PMID 38704736, 2024). "It was found that the lower the expression of PTGDR2, the higher the malignancy and the worse the prognosis of breast cancer patients." (PMID 38704736, 2024).
pulmonary TB (1 paper, 2023). "Our study identified unique gene signatures (IL-27, STAT1, IRF1, TLR4, IL-15, IL-2RA, IL-24, TGFβ, CD28, CD80, NFATC1, and PTGDR2) that discriminate active pulmonary TB from uninfected controls using unstimulated PBMCs." (PMID 37460564, 2023).
sarcoma (1 paper, 2022). A usually aggressive malignant neoplasm of the soft tissue or bone. "Gene expression analysis showed five genes (homeobox A10 (HOXA10), GATA binding protein 3 (GATA3), prostaglandin D2 receptor 2 (PTGDR2), thymocyte selection associated high mobility group box (TOX), and C-C motif chemokine receptor 3 (CCR3)) were dysregulated (p < 0.05) in sarcoma patients." (PMID 36005179, 2022). "Overall, sarcoma studies related to PTGDR2, CCR3, and HOXA10 are still lacking." (PMID 36005179, 2022).
serous ovarian cancer (1 paper, 2022). "On the other hand, the same amplitude of down-regulation of PTGES and PTGDR2 gene expression in the group with serous ovarian cancer grade G3 correlates with relapse-free survival at 6 months and the response to taxanes and platinum treatment, respectively." (PMID 35453789, 2022).